DLGAP5 (DLG associated protein 5)
Diseases named in the same sentence as DLGAP5 in open-access papers (continued):
Sharing a sentence is not in itself a finding about the gene and the disease.
non-small cell lung carcinoma (10 papers, 2019 to 2025). A group of at least three distinct histological types of lung cancer, including non-small cell squamous cell carcinoma, adenocarcinoma, and large cell carcinoma. "Schneideret al. demonstrated that DLGAP5 was a specific mitosis-associated genes correlate with poor prognosis for non-small cell lung cancer patients." (PMID 31139013, 2019). "DLGAP5 promotes non-small cell lung cancer (NSCLC) cell proliferation through modulation of the cell cycle, rather than apoptosis." (PMID 39100078, 2024). "The study reported that DLGAP5 was involved in related ovarian and non-small cell lung cancers." (PMID 37910672, 2023). "Among them, DLGAP5 could physically interact with PBK, TOP2A, and CDK1, and all mitosis-associated proteins correlated with poor prognosis for non-small cell lung cancer patients." (PMID 32426332, 2020).
pancreatic cancer (9 papers, 2020 to 2025). "Meanwhile, as a prognostic biomarker, DLGAP5 was associated with poor prognosis in colorectal, endometrial, breast, and pancreatic cancers." (PMID 36712920, 2023). "We believe that DLGAP5 is most closely associated to pancreatic cancer survival and can be used as a prognostic marker for pancreatic cancer." (PMID 32782440, 2020). "Hence, this study was designed to investigate the role of DLGAP5 as a biomarker in pancreatic cancer and explore the possible underlying mechanisms of DLGAP5 in tumorigenesis." (PMID 32782440, 2020). "DLGAP5 expression is significantly elevated in pancreatic cancer tissues and is correlated with patients’ survival and progression-free survival." (PMID 38144520, 2023). "DLGAP5 can be used as a prognostic indicator for pancreatic cancer and affect the occurrence and development of pancreatic cancer." (PMID 32782440, 2020). "To select the appropriate cell model for the next study, we first compared the expression levels of DLGAP5 in pancreatic cancer cells (PANC-1, SW1990, Capan-2, and BxPC-3)." (PMID 32782440, 2020). "Through the screening in Oncomine, 2 studies were found to involve DLGAP5’s expression in pancreatic cancer and normal tissues." (PMID 32782440, 2020). "In these studies, the expression level of DLGAP5 in the pancreatic cancer group was higher than in the normal group (P < 0.05)." (PMID 32782440, 2020). "The experimental results showed that when we knocked down the expression of DLGAP5 in pancreatic cancer cells, their proliferation ability was significantly inhibited, and their invasion and migration ability significantly decreased." (PMID 32782440, 2020). "The biological role of DLGAP5 in pancreatic cancer prognosis is currently unclear; therefore, it was chosen for further analysis." (PMID 32782440, 2020). "DLGAP5 was significantly expressed in pancreatic cancer, and its expression level had a significant effect on patients’ survival time and progression-free survival." (PMID 32782440, 2020). "This study aimed to investigate DLGAP5 expression in pancreatic cancer and explore the possible mechanisms and clinical value of DLGAP5 in tumorigenesis and tumor development." (PMID 32782440, 2020). "The advantage of this study is that the expression and biological behavior changes of DLGAP5 in pancreatic cancer are discussed for the first time using a combination of bioinformatics analysis and experiments." (PMID 32782440, 2020). "Knockdown of DLGAP5 inhibits pancreatic cancer cell proliferation, invasion, and migration." (PMID 38144520, 2023). "DLGAP5 was found to be differentially expressed in pancreatic cancer and related to prognosis." (PMID 32782440, 2020). "Furthermore, the biological behavior of DLGAP5 in pancreatic cancer was verified by cell function experiments." (PMID 32782440, 2020). "In this study, we screened out genes that were differentially expressed in pancreatic cancer and selected from them DLGAP5, which may be closely related to prognosis." (PMID 32782440, 2020). "It is believed that DLGAP5 may control tumor-related signaling pathways such as the cell cycle to pose influence on cell proliferation and then promote the incidence and development of pancreatic cancer." (PMID 32782440, 2020). "To screen out the genes closely related to the prognosis of pancreatic cancer from these differential genes, we used Kaplan–Meier to plot the survival curves of these differential genes and found that among these differential genes, the prognosis of the DLGAP5 gene was most significant." (PMID 32782440, 2020). "To further clarify the molecular mechanisms of DLGAP5 in pancreatic cancer, we performed functional experiments on DLGAP5 in Capan-2 and SW1990 cells to study the involvement of DLGAP5 in biological behavior." (PMID 32782440, 2020).
pancreatic cancer (continued). "The most prognostic gene, DLGAP5, was screened out, and the Oncomine and gene expression profiling interactive analysis (GEPIA) databases were used to analyze its expression in pancreatic cancer and other cancer tissues." (PMID 32782440, 2020). "Compared with the low expression group, patients with pancreatic cancer in the high expression group had much shorter OS and PFS, indicating that the DLGAP5 expression is related to the OS and disease-free survival of patients with pancreatic cancer." (PMID 32782440, 2020).
colorectal cancer (8 papers, 2012 to 2025). A primary or metastatic malignant neoplasm that affects the colon or rectum. "Our finding that the C allele is associated with increased DLGAP5 expression in tumors, suggests a potential mechanism by which this allele may promote tumor progression for colorectal cancer." (PMID 22363440, 2012). "Vittorio Branchi found that the knockdown of DLGAP5 led to a significant reduction of the invasion and migration in colorectal cancer." (PMID 35873473, 2022). "In addition, it has been reported that DLGAP5 may have a role in stem cell maintenance and survival and has been observed to be over-expressed in colorectal cancer cells." (PMID 22363440, 2012). "We observed an association between the low colorectal cancer risk allele (A) for rs10795668 at 10p14 and increased expression of ATP5C1 (q = 0.024) and between the colorectal cancer high risk allele (C) for rs4444235 at 14q22.2 and increased expression of DLGAP5 (q = 0.041), both in tumor samples." (PMID 22363440, 2012). "CCNA2, MAD2L1, DLGAP5, and RRM2 were all significantly related to the pathological stages of colorectal cancer and were also closely related to the stage of lymph node metastasis." (PMID 33519906, 2020). "Among them, we found that CCNA2, MAD2L1, DLGAP5, and AURKA were related to the overall survival (OS) of colorectal tumors, while RRM2 and AURKA had the relation between disease-free survival (DFS) and colorectal cancer." (PMID 33519906, 2020).
endometrial cancer (8 papers, 2013 to 2025). Primary or metastatic malignant neoplasm involving the endometrium (mucous membrane that lines the endometrial cavity). "DLGAP5 mutation was found in 6% of TCGA endometrial cancer samples, and the somatic mutation frequency accounted for 5.9%, most of which are missense mutations and relatively dispersed." (PMID 33312770, 2020). "Similarly, we hypothesized that the extent of methylation is also one of the essential mechanisms underlying the dysregulation of DLGAP5 expression in endometrial cancer." (PMID 33312770, 2020). "At the same time, the results revealed that the expression of DLGAP5 was firmly related to the poor prognosis of patients with endometrial cancer." (PMID 33312770, 2020). "Apart from DLGAP5, there were still 18 genes significantly correlated with the prognosis of endometrial cancer (P < 0.05)." (PMID 33312770, 2020). "This study found that, in endometrial cancer tissues, both RNA and protein expression levels of DLGAP5 were significantly higher than in normal tissues." (PMID 33312770, 2020). "Among them, DLGAP5 is the member most closely related to carcinoma, but there are very few studies in the field of endometrial cancer." (PMID 33312770, 2020). "Kaplan–Meier survival analysis announced that the expression level of DLGAP5 was negatively correlated with the overall survival of patients with endometrial cancer." (PMID 33312770, 2020). "DLGAP5 is a potential oncogene with cell cycle regulation, and its overexpression can predict the poor prognosis of patients with endometrial cancer." (PMID 33312770, 2020). "Subsequently, the prognostic meaning of DLGAP5 in patients with endometrial cancer was explored based on survival data from TCGA-UCEC (n = 541)." (PMID 33312770, 2020). "This study was aiming to analyze the role of DLGAP5 in tumorigenesis and development and to investigate its prognostic significance of patients with endometrial cancer." (PMID 33312770, 2020). "To sum up, we used TCGA-UCEC and HPA to find that both RNA and protein expression levels of DLGAP5 in endometrial cancer tissues were higher than normal endometrial tissues, and the consistency was verified in clinical samples." (PMID 33312770, 2020). "The expression of DLGAP5 in endometrial cancer tissues was significantly higher than that in adjacent tissues (P < 0.001)." (PMID 33312770, 2020). "As a candidate target for the diagnosis and treatment of endometrial cancer, it is worthwhile to make further study to reveal the carcinogenicity of DLGAP5 and the mechanism of its resistance of organisms." (PMID 33312770, 2020). "By contrast, we found that the expression of DLGAP5 in endometrial cancer tissues was significantly higher than that in normal endometrial tissues (P < 0.0001)." (PMID 33312770, 2020). "To clarify the clinical relevance of DLGAP5, we used the Human Protein Atlas database to analyze the expression of DLGAP5 in normal endometrial tissues and endometrial cancer tissues." (PMID 33312770, 2020). "Back to the clinical samples, taking RT-qPCR to identify the differential expression level of DLGAP5 in tumor and para-cancer tissues of 16 pairs of patients with endometrial cancer." (PMID 33312770, 2020). "As a prognostic factor, high expression of DLGAP5 is unfavorable in endometrial cancer." (PMID 33312770, 2020). "This may be a potential mechanism for DLGAP5 overexpression in endometrial cancer, which needs to be clarified in further studies." (PMID 33312770, 2020). "Transcriptome data from TCGA-UCEC, immunohistochemical data from HPA, and RT-qPCR results from clinical samples were used for triple validation to confirm that the expression of DLGAP5 in endometrial cancer tissues was significantly higher than that in normal endometrial tissues." (PMID 33312770, 2020). "Studies have shown that DLGAP5 may be a potential clinical marker for patients with endometrial cancer and exhibit a variety of tumor-related biological characteristics." (PMID 33312770, 2020).
endometrial cancer (continued). "For this research, we verified the differential expression of DLGAP5 (ENSG00000126787) in endometrial cancer and normal endometrial tissue with the help of bioinformatics tools, further analyzed the possible mechanism of its dysregulation, and assessed the significance of its prognostic." (PMID 33312770, 2020). "Therefore, we concluded that the upregulation of DLGAP5 was a critical mechanism leading to abnormal proliferation of endometrial cancer cells." (PMID 33312770, 2020). "Consequently, taking advantage of the hypoxic-controlled biological properties of DLGAP5, hypoxia-related therapies targeted at tumors may benefit patients with endometrial cancer." (PMID 33312770, 2020). "By comparison, among the 11 endometrial cancer tissues examined, moderate and negative DLGAP5 staining were in a clear minority (18%), and the majority was low-stained (64%)." (PMID 33312770, 2020). "Although the abnormal expression of DLGAP5 in endometrial cancer has been mentioned in a few literatures, it has not been discussed in depth." (PMID 33312770, 2020). "Among these, we found that two previously implicated stem cell associated markers, the disks large homolog 7 (DLG7, also known as DLGAP5) and the maternal embryonic leucine zipper kinase MELK transcripts were elevated in endometrial cancer specimens compared to controls." (PMID 23785665, 2013). "Although no related studies have performed in endometrial cancer, further exploration for the prognostic value of DLGAP5 may yield far-reaching implications." (PMID 33312770, 2020). "DLGAP5 is a recently identified cell cycle-regulation gene not reported in endometrial cancer." (PMID 33312770, 2020).
glioma (8 papers, 2015 to 2024). A benign or malignant brain and spinal cord tumor that arises from glial cells (astrocytes, oligodendrocytes, ependymal cells). "Our data showed that momordicine I can induce cell cycle arrest and inhibit DLGAP5 expression in glioma cells, indicating that momordicine I has therapeutic potential in glioma treatment." (PMID 37534227, 2023). "Consistent with the online analyses, we found that down-regulation of LMNB1 and DLGAP5 with siRNA inhibited the proliferation of glioma cells." (PMID 33956061, 2021). "Together, LMNB1 and DLGAP5 were two potentially novel molecular biomarkers for diagnosis and prognosis of glioma." (PMID 33956061, 2021). "First, we detected the basal protein level of LMNB1 and DLGAP5 in several glioma cell lines including LN229, U87, primary cultured GBM cell (GBM), U251, T98G." (PMID 33956061, 2021). "After searching for TCGA and CGGA datasets, we found that the expression of LMNB1 and DLGAP5 were up-regulated in glioma." (PMID 33956061, 2021). "Our study confirmed that LMNB1 and DLGAP5 were up-regulated in gliomas, and patients with high expression of LMNB1 or DLGAP5 had poor survival rate." (PMID 33956061, 2021). "LMNB1 and DLGAP5 were two potentially novel molecular biomarkers for diagnosis and prognosis of glioma." (PMID 33956061, 2021). "Examined by EdU assay and CCK-8 assay, we found that silence of DLGAP5 inhibited the proliferation of glioma cells." (PMID 33956061, 2021). "We analyzed the expression of LMNB1 and DLGAP5 in glioma patients with different histological subtype, molecular subtype, progression stage and IDH status in TCGA and CGGA databases." (PMID 33956061, 2021). "Momordicine I induced cell cycle arrest by targeting DLGAP5 in glioma cells." (PMID 37534227, 2023). "The expression of DLGAP5 was also found to be elevated in glioma." (PMID 37534227, 2023). "In addition, LMNB1 and DLGAP5 were selected for further analyses due to their high expression in gliomas and were verified by using our cohort." (PMID 33956061, 2021). "In conclusion, these results showed that LMNB1 and DLGAP5 may be used to predict the prognosis of glioma patients." (PMID 33956061, 2021). "Furthermore, we researched the roles of LMNB1 and DLGAP5 in glioma cell proliferation by silencing LMNB1 and DLGAP5." (PMID 33956061, 2021). "Silence of LMNB1 and DLGAP5 inhibited the proliferation of glioma cells." (PMID 33956061, 2021). "Taken together, our analyses showed that LMNB1 and DLGAP5 were highly expressed in glioma and negatively associated with patient survival, indicating that LMNB1 and DLGAP5 were important for the development and prognosis of glioma." (PMID 33956061, 2021). "Our work indicated that DLGAP5 may promote glioma progression by speeding the G0/G1 phase progression." (PMID 33956061, 2021). "Together, these data indicated that LMNB1 and DLGAP5 were up-regulated in glioma and might play specific roles in different molecular subtype." (PMID 33956061, 2021). "Similarly, we chose siDLGAP5-3, which exhibited the highest silencing efficiency on DLGAP5, to examine the roles of DLGAP5 on glioma proliferation." (PMID 33956061, 2021). "Since both of LMNB1 and DLGAP5 were up-regulated in glioma tissues, we therefore down-regulated LMNB1 and DLGAP5 with siRNAs to detect whether silence of LMNB1 or DLGAP5 inhibits the proliferation of glioma cells." (PMID 33956061, 2021). "Furthermore, we confirmed the translation expression level of the hub genes using the HPA database, and the prognostic biomarkers were found to be stained strongly or moderately.: SMC4, OCR1, CDCA8, and DLGAP5, indicating that these hub genes were translated more in glioma samples." (PMID 38926605, 2024). "Furthermore, silence of LMNB1 and DLGAP5 inhibited the proliferation of glioma cells." (PMID 33956061, 2021). "Other co-expressed genes are also involved in the progression of glioma, such as KIF2C, DLGAP5 and CCNB1." (PMID 36040678, 2022).
glioma (continued). "Among four glioma subtypes (proneural, mesenchymal, classical and neural), the proneural subtype exhibited the highest expression level of LMNB1 and DLGAP5, and the neural subtype expressed the lowest levels." (PMID 33956061, 2021). "The analysis results showed that glioma patients with high expression of LMNB1 and DLGAP5 exhibited worse overall survival rate." (PMID 33956061, 2021). "We found an overexpression of DLGAP5, NEK2, and PBK, while the expression of SF1, PTEN, ATRX, and DAXX was downregulated in tumor tissues as compared to normal tissues of the patients with glioma." (PMID 35095717, 2021). "Similarly, Grade IV gliomas showed the highest LMNB1 and DLGAP5 expression level in CGGA RNAseq datasets." (PMID 33956061, 2021). "Compared with non-tumor tissues, LMNB1 and DLGAP5 were highly expressed in glioma tissues, which was reflected in the research of Sun and Murat." (PMID 33956061, 2021).
liver cancer (8 papers, 2013 to 2025). An epithelial or non-epithelial malignant neoplasm that arises from the liver. "We also found that the hub upregulated genes in this network—MCM3, BUB1B, DLGAP5, DIP5, ECT2—have been linked to liver cancer according to wide literature reports." (PMID 39628446, 2024). "The CpG island methylation level of DLGAP5 promoter can directly regulate the amplification of DLGAP5, achieve epigenetic regulation, and promote the occurrence of liver cancer." (PMID 33312770, 2020). "To understand the biological function of DLGAP5 in liver cancer, we knocked down DLGAP5 gene expression by RNA interference and observed a significant suppression of cell growth and colony formation." (PMID 24324629, 2013). "To better understand the function of DLGAP5, we selected liver cancer cell lines for study." (PMID 34454476, 2021). "Meantime, we observed a tendency of DLGAP5 high expression relating to poorer OS, PFS (Progress-free survival), RFS, and DSS (Disease-specific survival) prognosis in liver cancer (all P < 0.001)." (PMID 34454476, 2021).
adrenocortical tumors (5 papers, 2011 to 2021). "DLGAP5, disc large homolog associated protein 5, has a pivotal role in spindle assembly and chromosomal segregation during mitosis, which has been found to be unregulated in several cancer types, including OC, colorectal cancer (CRC), HCC, and adrenocortical tumors." (PMID 31729978, 2019). "The combination of BUB1B, DLGAP5, and PINK1 can serve as a predictor of a poor outcome in adrenocortical tumors." (PMID 35095717, 2021).
clear cell renal cell carcinoma (4 papers, 2023 to 2025). "DLGAP5 has been found to be up-regulated in clear cell renal cell carcinoma, and its knockdown suppressed cell viability, proliferation, migration, and invasion." (PMID 37958803, 2023).